IGF1 (insulin like growth factor 1)
Diseases named in the same sentence as IGF1 in open-access papers (continued):
Sharing a sentence is not in itself a finding about the gene and the disease.
infection (121 papers, 2005 to 2026). The state of being infected such as from the introduction of a foreign agent such as serum, vaccine, antigenic substance or organism. "The presence of a concurrent neurological deficit following the infection was found to be associated with lower levels of IGF-1." (PMID 39787566, 2025). "Earlier studies suggested that the insulin/IGF-1 signaling pathway has been involved in conferring resistance against pathogenic infections." (PMID 40401953, 2025). "The gene encoding IGF-1 was more highly expressed in the cluster 2 macrophages at 6 w after infection, and its receptor, IGF-1r, was more highly expressed in the neutrophils and macrophages." (PMID 39590301, 2024). "An earlier report documented an inverse association between infections, systemic inflammation, and plasma IGF‐1 concentration, and that seasonal changes in children's plasma IGF‐1 concentration coincided with changes in their length gain velocity." (PMID 36111423, 2023). "In summary, asymptomatic infections were common in apparently healthy children in rural Malawi, and infection‐induced systemic inflammation was associated with reduced plasma IGF‐1 concentration, leading to impaired linear growth." (PMID 36111423, 2023). "Inflammation is often caused by infections, and both symptomatic and asymptomatic infections have been associated with reduced plasma concentrations of IGF‐1 among infants and young children in low‐income settings." (PMID 36111423, 2023). "Hosts infected with Plasmodium demonstrate increased blood insulin concentrations, which trigger the insulin/IGF-1 signaling pathway in Anopheles mosquitos, hereby increasing mosquito susceptibility to infection, lifespan and transmission." (PMID 35385472, 2022). "Animals lacking Igf1 had higher worm counts than their wildtype counterparts and IGF1 was associated with acute wound healing and reduced lung damage/hemorrhage during early infection." (PMID 36569914, 2022). "IGF1 decreases in response to pro-inflammatory cytokines, such as tumor necrosis factor-α, interleukin (IL) 1β, and IL-6; low circulating levels of IGF1 are associated with infection, trauma, and aging." (PMID 32692761, 2020). "Infection and inflammation were linked to evidence of GH resistance, whereas levels of GH, IGF-1, and IGFBP-3 were associated with growth indices independent of hsCRP." (PMID 27712965, 2017). "Genetic experiments suggested that this infection phenotype is likely caused by modulation of the DAF-2 insulin/IGF-1 signalling pathway." (PMID 22672310, 2012). "Our data also suggest that IGF and associated pathways may also participate in shunt infection as there is a significant body of data demonstrating the many functions of IGF-1 in the CNS." (PMID 36864917, 2023). "Disregulation or disturbances of IGF-1 levels in serum and its receptor may be linked with susceptibility to infections and subsequent diseases in children." (PMID 24303053, 2013). "IGF-1 levels were considerably lower in the infection group, both in absolute terms and when adjusted for sex and age (P < 0.001)." (PMID 39787566, 2025). "Our analysis also revealed that patients who contracted the infection in the neonatal period had lower IGF-1 levels compared to children who acquired the CNS infection at a later age." (PMID 39787566, 2025). "The remaining host miRNAs principally regulate the expression of Igf1 (increased in expression), which was most evident at 5 days post-infection and notably these miRNAs were primarily from the miRNA cluster on chromosome 12." (PMID 39344634, 2024). "The qRT-PCR results confirmed that the expression of IGF-1 and IGF-1r increased at 6 w after infection." (PMID 39590301, 2024). "The results showed that after lentivirus stabilization screening, approximately 70% of the cells presented fluorescent expression, indicating that IGF1 overexpression via lentivirus infection was successful." (PMID 39766763, 2024).
infection (continued). "The results of the present study showed a significant reduction in the serum IGF-1 levels positively regulated by Ghrelin during the late stage of infection in E. g-infected mice." (PMID 39436864, 2024). "The main objective was to investigate clinical biomarkers that would predict the progression of infection severity, with a special focus on circulating IGF-1; H-FABP, and ETP." (PMID 37189123, 2023). "Results of the current work, however; demonstrated that low levels of circulating IGF1 in patients with mild infection (score 1) escalate concomitantly with progressive infection scores, reaching the maximum in critical cases (score 4)." (PMID 37189123, 2023). "Systemic inflammation, leading to reduced plasma and tissue concentration of IGF‐1 and possibly other growth‐promoting hormones, constitutes a possible mechanism linking infections to growth faltering." (PMID 36111423, 2023). "Compared to light infection intensity at baseline, participants with heavy or moderate infection intensity had significantly lower concentrations of IGF-1 measured at baseline, 6-month, and 12-month visits." (PMID 36197916, 2022). "The top 5 downregulated genes in the UB of CIE mice at 1 wk post-infection included Igf1, Col6a3, Myrf, Itga7, and Serpinf1." (PMID 36490282, 2022). "Transcription expression of mTOR and IGF1 increased at 6 h after infection, but gradually decreased after 12 h." (PMID 36423079, 2022). "IGF-1 concentrations were significantly lower for those with moderate and heavy infection intensity compared to light infection intensity at baseline, 6-month, and 12-month visits." (PMID 36197916, 2022). "IGF-1 concentrations were significantly lower among children with high and moderate vs low intensity infections at each study visit." (PMID 36197916, 2022). "Only on day 7 post infection, parasite levels and percentage metacyclics tend to be highest in the flies fed on blood with normal IGF-1 concentrations (medium)." (PMID 35385472, 2022). "Plasma levels of insulin-like growth factor 1 (IGF-1) were increased in COS-supplemented pigs 48 h post-infection with E. coli K88 and remained greater than that of the un-supplemented challenged pigs." (PMID 34573610, 2021). "What is more, we found out that the levels of IL1β, IL8, RANTES (CCL5), MCP-2, and IGF1 were significant higher in early stage of infection." (PMID 35095832, 2021). "The infection with Ad-26b-5p, Ad-204-5p, and Ad-497-3p significantly decreased the IGF-1-induced expression of LC3 II and Beclin 1 proteins in cardiomyocyte hypertrophy (P < 0.01)." (PMID 32140172, 2020). "Ad-26b-5p, Ad-204-5p, and Ad-497-3p infections significantly decreased the IGF-1 induced expression of LC3 II in cardiomyocyte hypertrophy, as reflected by reduced fluorescence (P < 0.01, P < 0.05, P < 0.01, respectively)." (PMID 32140172, 2020). "The level of IGF1 mRNA expression peaked at 48 h post-infection, which was 6.35 ± 0.30 times higher than that of the Mock controls." (PMID 31849847, 2019). "In A549 cells infected with different MOIs of PR8, the level of IGF1 mRNA expression increased following the increasing of MOI at 48 h post-infection." (PMID 31849847, 2019). "On days 3, 5, 7, and 9 post-infection, the mice lung tissue was collected to detect the expression changes in IGF1 mRNA and protein." (PMID 31849847, 2019). "The level of IGF1 protein expression was also upregulated at 12, 24, 48, and 72 h post-infection of PR8 and following the increasing of MOI at 48 h post-infection in A549 cells." (PMID 31849847, 2019). "On day 7 post-infection, IGF1 mRNA increased to 5.81 ± 0.623 times that of the control group and decreased slightly on day 9 post-infection." (PMID 31849847, 2019). "The level of IGF1 mRNA expression decreased slightly at 72 h post-infection but still reached 4.23 ± 0.18 times that of the Mock group." (PMID 31849847, 2019).
infection (continued). "Non-vaccinated, clinically healthy animals (− 4.72%) and pigs with clinical signs of infection (− 20.9%) had lower IGF-1 concentrations in the serum at the time of dissection." (PMID 30382876, 2018). "C57BL/6 mice were infected with Colombian strain Trypanosoma cruzi and treated with MSCs, MSC_IGF-1, or vehicle (saline) six months after infection." (PMID 30140292, 2018). "We have previously shown that IGF-1 gene expression is increased in the heart and skeletal muscles in the acute phase of infection with T. cruzi in mice." (PMID 30140292, 2018). "During infection with the helminth parasite Nippostrongylus braziliensis, AAMΦ-induced IL-10 and IGF1 suppress the pro-inflammatory Th17 and neutrophil response." (PMID 29352310, 2018). "Through enhanced IGF1-signalling PSG promotes the alternative activation of macrophages recruited to the site of infection and increases their arginase levels." (PMID 29352310, 2018). "Using uninfected and L. mexicana-infected sand flies (with mature, transmissible infections: average ± SD, 3 x 104 ± 1.63 x 104 promastigotes; 58% ± 9% metacyclics per gut), we compared dermal IGF1 expression in response to individual sand fly bites." (PMID 29352310, 2018). "The mRNA expression levels of the chemokines Ccl3 and Cxcl12 and the levels of Igf1 in thymocytes were clearly upregulated due to protein malnutrition or infection conditions separately (Ccl3 p < 0.01; Cxcl12 p < 0.05 and Igf1 p < 0.001)." (PMID 28397794, 2017). "In particular, it would be interesting to examine IGF-1 and associated PAPP-A2 expression levels early in the infection process and as early as four dpi as reported for another murine model." (PMID 24939584, 2014). "In particular, levels of IGF1 in blood of healthy humans can fall from 0.09 μM to below 0.006 μM during severe infections with P. falciparum and Plasmodium vivax." (PMID 24968248, 2014). "Recent studies indicate that cord blood IGF-1 is a key regulator of neonatal immune responses in maturation and infection, particularly by suppressing pro-inflammatory Th1 responses." (PMID 24303053, 2013). "DAF-2 insulin/IGF-1 signalling is one of the most extensively studied pathways regulating host infection outcomes in C. elegans." (PMID 22672310, 2012). "These infections impact liver health and decrease plasma IGF-1 in calves resulting in reduction of somatic growth by up to 48%, while causing no signs of clinical disease other than subtle reddening of the conjunctiva." (PMID 23024776, 2012). "IGF1 also modulates immune cells, and its alteration during infection may drive immune dysregulation." (PMID 41227320, 2025). "The IGF-1 signaling pathway was significantly weakened at 10 w after infection." (PMID 39590301, 2024). "Future studies should document whether IGF-1 supplementation to preterm infants affects immune development and sensitivity to infection." (PMID 37648745, 2024). "Moreover, IGF2 secretion was significantly increased upon rHSVQ infection while IGF1 was unaffected as confirmed by ELISA." (PMID 38853689, 2024). "However, the serum IGF-1 levels were significantly elevated in the early stage of infection in E. g-infected mice and were significantly positively correlated with Ghrelin." (PMID 39436864, 2024). "This hypothesis was further supported by the results of logistic regression that demonstrated IGF-1 predictive power of mild-to-severe infection transition, in terms of higher values of β-coefficient and significance with each higher severity score." (PMID 37189123, 2023). "There was a significant interaction between diet and infection on igf1 mRNA levels in the liver." (PMID 37958062, 2023). "Results revealed that both serum IGF-1 and H-FABP, as well as oxygen saturation, were significantly associated with progressive infection severity, suggesting that higher levels of serum IGF-1 and H-FABP, and lower oxygen saturation are more likely associated with progressive severity." (PMID 37189123, 2023).
infection (continued). "Differently, severe immunodeficiency is observed in another form of GH insensitivity due to a mutation in the signal transducer and activator of transcription 5B (STAT5B) gene, with reduced IGF-1 production, impaired response to infections and high production of prolactin (PRL)." (PMID 37426675, 2023). "For example, long-lived mutants in the insulin/IGF-1 signaling pathway are resistant to heat, oxidative stress, heavy metals, protein misfolding, and pathogen infection." (PMID 35966651, 2022). "However, this latter outcome is not without precedent, as PI3K-dependent/AKT-independent apoptosis inhibition has also been reported following treatment with IGF-1 and after infection by L. major." (PMID 35873156, 2022). "Higher IGF-1 levels seem to rather negatively impact the infection." (PMID 35385472, 2022). "The present study enrolled children infected with S. mansoni in Brazil to examine a) the relationships between infection intensity (egg burden), gut health markers, and IGF-1 and b) the longitudinal impact of S. mansoni treatment [praziquantel (PZQ)] on gut health markers and IGF-1." (PMID 36197916, 2022). "As the source of IGF1 was mainly from plasma B cells in stage A, it might be a key factor in regulating immune responses in early stage of infection." (PMID 35095832, 2021). "Then, the IGF-1 treated H9C2 cells were subjected to adenovirus-mediated miRNA infection." (PMID 32140172, 2020). "IGF1-blockade efficiently reduced the virulence of Leishmania infection from sand fly bite transmission indicating that it is essential to the function of PSG during natural infection." (PMID 29352310, 2018). "We hypothesize that the high susceptibility of dorsal-zone OSNs to damage is facilitated by a decrease in insulin/IGF1 signaling and high chance of infection." (PMID 30470811, 2018). "Moreover, treatment of broilers with Na-butyrate increased the expression level of IGF-1 and decreased the DNA fragmentation induced by NE infection." (PMID 27284219, 2016). "The PI3K-Akt pathway participated in early infection of some exogenous avian leucosis viruses and could mediate IGF-1 survival during the otic neuronal progenitor phase of early inner ear development." (PMID 27820849, 2016). "Body length, BMC and BMD, but not body mass, are rescued by infection of two-day-old ksr2−/− mice with a recombinant adenovirus encoding human IGF-1." (PMID 27561547, 2016). "Insulin-like growth factor binding proteins (IGFBPs) or IGFBP proteases could also be modulating the local availability and activity of IGF-1 during the infection." (PMID 24967908, 2014). "An IGF-1 induced reduction of IFN-γ, or other Th1 polarized immune responses in neonates could reduce the risk of hyper-inflammatory responses to both systemic and local infections." (PMID 37648745, 2024). "As higher IGF-1 concentrations are positively associated with growth rates in calves, being born SGA may limit their ability for catch-up growth in the early postnatal period, at which time calves are especially sensitive to infection." (PMID 39123682, 2024). "The gene expression levels of TGF-β and IGF-1, which are produced by anti-inflammatory/restorative macrophages and promote repair and regeneration of damaged tissues, were significantly increased at 36 h post-infection to at least 6 dpi and then declined in the recovery phase." (PMID 34305887, 2021). "Our results indicate that a component of the PSG promotes IGF1-signalling in a similar way by enhancing receptor and ligand expression in dermal macrophages during the early phase of infection when macrophage polarisation can significantly influence the course of infection." (PMID 29352310, 2018). "In addition, the infection with C. perfringens and supplementation with Na-butyrate significantly increased the expression level of IGF-1 compared with that in birds infected with C. perfringens alone (Figure-4) provided that it was still significantly lower than the negative control group." (PMID 27284219, 2016).
infection (continued). "Logistic regression analysis revealed that oxygen saturation; serum IGF-1, and H-FABP can significantly predict the infection progression (P < 0.001 each)." (PMID 37189123, 2023). "In this study, the IGF1, which regulates cell growth and proliferation, acting as a potent inhibitor of apoptosis, was clearly downregulated during DTMUV infection." (PMID 35585616, 2022). "The contribution of IGF-1 and IGF-1R to the mechanism of infection has been well documented in several virological studies, including studies on pneumonic viruses." (PMID 34452353, 2021). "Compared with the Mock-infected controls, the level of IGF1 mRNA expression in A549 cells increased gradually at 12, 24, and 48 h after PR8 infection at a MOI of 0.5." (PMID 31849847, 2019). "The level of IGF1 mRNA expression in the lung tissue gradually increased at days 3, 5, and 7 after PR8 infection." (PMID 31849847, 2019). "Infection with IGF1 (ADIGF1) significantly increased ALP activity and mRNA expression levels of Runx2 and OPN compared to infection with control recombinant adenoviruses (ADGFP)." (PMID 28387248, 2017). "Links between infections, inflammatory markers such as C-reactive protein (CRP), and levels of IGF-1 recently have been demonstrated in a cohort of young children followed in Zimbabwe." (PMID 27712965, 2017). "The systems biology analysis identified multiple immune system and inflammation molecules (e.g., STAT3, STAT1, CEBPB, JUN, IGF1, SPP1, NFKB2, IL-1β, and CSF1) as master regulators that are activated upon infection." (PMID 26865111, 2016). "The effects of insulin and IGF1 on IIS in A. stephensi are distinct and likely dictate the markedly different effects of these growth factors on lifespan and infection." (PMID 24968248, 2014). "Only FGF-1 was increased in early stage infection and other growth factors such as FGF-2 and IGF-1 were highly induced from 14 days after infection." (PMID 24351861, 2013). "Expression levels of keratinocyte growth factor (KGF), insulin-like growth factor-1 (IGF secreted by intraepithelial lymphocytes) and macrophage-derived factors were highly up-regulated during the Late Phase of infection." (PMID 22912686, 2012). "Use of the C. elegans model has also delineated several conserved host pathways modulating infection outcomes, including the p38 mitogen-activated protein kinase (MAPK), TGF-β and DAF-2 insulin/IGF-1 signalling pathways." (PMID 22672310, 2012). "It is remarkable that CGRP has been described to attenuate inflammation, to induce IGF‐1 and thus may qualify as a major regulator of TBI‐induced acceleration of wound healing and infection protection." (PMID 40879095, 2025). "From our multivariable linear regression analysis, the reduction in IGF-1 was greater the earlier the CNS infection occurred, regardless of the type of infection contracted." (PMID 39787566, 2025). "Adjunctive therapies such as serum eye drops, topical growth factors, polysulfated glycosaminoglycans, substance P, insulin-like growth factor-1 (IGF-1), and prophylactic topical antibiotics have been employed to enhance epithelial healing and prevent infection." (PMID 40723566, 2025). "The regression analysis suggested that the reduction in IGF-1 was more pronounced the earlier the CNS infection occurred, irrespective of infection type." (PMID 39787566, 2025). "First, IGF‐1's blood–brain barrier (BBB) penetration is modulated by serum‐binding proteins (IGFBP and others), and intracranial pumps are clinically limited to severe conditions (e.g., refractory epilepsy) due to infection risks." (PMID 41414737, 2025). "In addition, the insulin-like growth factor-1 (IGF-1), visfatin, and secretory phosphoprotein 1 (SPP1) signaling pathways were increased after infection with schistosomes." (PMID 39590301, 2024).